TCF7L2 (transcription factor 7 like 2)
Diseases named in the same sentence as TCF7L2 in open-access papers (continued):
Sharing a sentence is not in itself a finding about the gene and the disease.
Insulin resistance (continued). "Among numerous genetic loci, TCF7L2 (rs7903146), KCNQ1 (rs2237892), and KCNJ11 (rs5219) are associated with β-cell function, insulin resistance, and insulin action in GDM." (PMID 37107681, 2023). "TCF7L2 has an important role in glucose homeostasis, the generation of insulin resistance, and lipid metabolism." (PMID 35237941, 2023). "Recent evidence reveals a more complex regulatory role for TCF7L2 gene and its adipose tissue expression in mediating WNT pathway related metabolic effects that are associated with Insulin resistance and T2DM." (PMID 36263318, 2022). "Deletion of Tcf7l2 in mature adipocytes in mice leads to whole-body glucose intolerance and hepatic insulin resistance, which is concomitant with increased subcutaneous adipose tissue mass and adipocyte hypertrophy." (PMID 35874808, 2022). "TT/CT genotypes of the rs7903146 polymorphic form of TCF7L2 gene are also associated with higher HOMA-IR and lower serum adiponectin levels both of which are markers of higher insulin resistance." (PMID 36263318, 2022). "Although the role of insulin resistance in inducing inflammation has been identified, the effect of TCF7L2 gene on inflammation has been less investigated." (PMID 35585604, 2022). "The use of a humanoid mouse model overexpressing TCF7L2 showed that the extra copy added to TCF7L2 induces insulin resistance." (PMID 34440181, 2021). "TCF7L2 expression was also found to be downregulated in human subjects with impaired glucose tolerance and adipocyte insulin resistance." (PMID 33186544, 2020). "Our results demonstrated that the extent of increases in some metabolic variables (body weight, insulin resistance, AUCg, and insulin) actively influences the TCF7L2 expression in the liver, skeletal muscle, and adipose tissues." (PMID 29713286, 2018). "Olanzapine challenge induced remarkably increased body weight, fasting insulin, homeostasis model assessment-insulin resistance index, and TCF7L2 protein expression in liver, skeletal muscle, and adipose tissues." (PMID 29713286, 2018). "Conversely, mice that overexpress Tcf7l2 display reciprocal phenotypes, including increased plasma insulin levels and glucose intolerance due to peripheral insulin resistance, indicating that overexpression of Tcf7l2 leads to a type 2 diabetic phenotype." (PMID 25398947, 2015). "In summary, we have provided the evidence for the influence of insulin-resistance on the isoform-specific expression of TCF7L2 in the liver, which contributes to the increased glucose production and the resultant hyperglycemia in mammals." (PMID 23028378, 2012). "Expression of medium and short isoforms of TCF7L2 was greatly diminished in livers of diet-induced and genetic mouse models of insulin resistance, prompting us to delineate the functional role of these isoforms in hepatic glucose metabolism." (PMID 23028378, 2012). "We found that hepatic expression of medium and short isoforms of TCF7L2 was specifically reduced in mouse models of insulin resistance." (PMID 23028378, 2012). "We found that hepatic expression of nuclear isoforms of TCF7L2 was reduced in mouse models of insulin resistance." (PMID 23028378, 2012). "Interaction between CDKN2B rs10811661 and TCF7L2 rs4506565 variants were significant (β = 1.6667, p = 0.0002, 0.0341, and 0.0012 for main and interacting effects), and it was associated with high slope values, which may be expressed as an increase in insulin resistance across ages." (PMID 20018066, 2009). "TCF7L2 has been strongly linked to elevated HbA1c levels and an increased risk of T2D, FTO rs9939609 variant has been linked to high HbA1c levels and insulin resistance, and CAPN10 has been associated with insulin resistance and T2D." (PMID 39275336, 2024). "Moreover, TCF7L2 functions as a co-activator of p65 to potentiate inflammatory cytokine production in macrophages to aggravate induced chronic inflammation and insulin resistance in mice." (PMID 35237941, 2023).
Insulin resistance (continued). "Importantly, the TCF7L2 mRNA expression is downregulated in humans with impaired glucose tolerance and adipocyte insulin resistance." (PMID 35874808, 2022). "However, it will not be possible from this study to say that it is only the overexpression of TCF7L2 gene in visceral adipose tissue that results in insulin resistance." (PMID 36263318, 2022). "Concerning the GO term adherent junctions, TCF7L2 is one of the top loci associated with increased T2D risk; epigenetic modifications showed by EWAS reporting lower methylation in SAT in T2D individuals, and association with BMI and insulin resistance." (PMID 33803198, 2021). "It has been shown that TCF7L2 is associated with reduced insulin levels rather than increased insulin resistance." (PMID 34073870, 2021). "Similarly, lower DNA methylation of TCF7L2 in SAT was associated with BMI; and associated with insulin resistance in adipose tissue samples from lean and obese patients pre- and post-Roux-en-Y gastric bypass." (PMID 33803198, 2021). "However, TCF7L2 activation also regulates Wnt signaling during adipogenesis, and in vivo deactivation of TCF7L2 protein in mature adipocytes results in hepatic insulin resistance and systemic glucose intolerance." (PMID 33186544, 2020). "In addition, we found that olanzapine-induced body weight gain and insulin resistance actively influence the expression of TCF7L2 in liver and skeletal muscle, and elevated level of insulin determines the increased expression of TCF7L2 in adipose tissue." (PMID 29713286, 2018). "We did not replicate associations with several well-known T2DM genes, including TCF7L2, FTO, IRS1, and KCNQ1, in our Han Chinese population (In our data set, the FTO gene SNPs yielded some associations with insulin resistance related phenotypes in quantitative analyses." (PMID 26139146, 2015). "Depletion of hepatic TCF7L2 promoted higher glucose levels, suggesting that reduced expression of certain isoforms of TCF7L2 under insulin resistance might be in part responsible for the hyperglycemia in that setting." (PMID 23028378, 2012). "Our current finding suggests that TCF7L2, together with JAZF1 variants, may indirectly impart insulin resistance through joint modulation of lipid metabolism." (PMID 20018066, 2009). "Previously, it was thought that the TCF7L2 variant was only associated with β-cell function failure but not insulin resistance." (PMID 20018066, 2009). "In animal models, adipocyte-specific deletion of Tcf7l2 combined with high-fat diet leads to early-onset glucose intolerance, insulin resistance, weight gain, and adipose expansion, with glucose dysregulation evident by day 3 and insulin resistance by 3 months." (PMID 41153348, 2025). "Although previous studies have suggested that impairment in β-cell function predisposes the risk-allele carriers of the TCF7L2 variants to the progression of T2DM, the dysfunction in β-cell may be due to the insulin resistance that is more pronounced in healthy T-allele risk carriers." (PMID 36155628, 2022). "Moreover, it has been recently demonstrated that mice overexpressing TCF7L2 display reciprocal phenotypes, including increased plasma insulin levels, and glucose intolerance due to peripheral insulin resistance, indicating that overexpression of TCF7L2 leads to a phenotype of T2DM." (PMID 29736187, 2018). "This is consistent with previous studies that reported that the Wnt pathway was downregulated in WAT in mice that were fed a HF diet, db/db mice, and Zucker (fa/fa) rats, suggesting that chronic insulin resistance may lead to a reduction of TCF7L2 transcriptional activity." (PMID 27527335, 2016). "Thus TCF7L2 might play some role in the adipogenesis resulting in the deposition of triglycerides in peripheral tissues leading to insulin resistance." (PMID 23577093, 2013).
Insulin resistance (continued). "Also oxidative stress through TCF7L2/NF-kB/MAPK/HIF1A/SREBP regulatory cascade via insulin, MAPK and Calcium signaling pathways, may activate inflammatory responses than in turn causes insulin resistance." (PMID 20942928, 2010). "Specifically in mature adipocytes in vivo, disabling the TCF7L2 protein by eliminating the HMG-box DNA-binding domain resulted in overall glucose intolerance and insulin resistance in the liver." (PMID 38396716, 2024). "Tcf7l2 overexpression in BAC/+ mice results in increased insulin secretion and glucose intolerance after high fat diet (HFD) due to peripheral insulin resistance." (PMID 25398947, 2015). "DIO-mediated or genetic haploinsufficiency of TCF7L2 promotes hyperglycemia and insulin resistance in mouse models, suggesting that dysregulation of TCF7L2 expression in the liver might be a critical contributor for the insulin resistance and hyperglycemia in humans." (PMID 23028378, 2012). "Furthermore, decreased expression of medium and short isoforms was also pronounced in the livers of db/db mice compared with control, suggesting that hepatic insulin resistance might be correlated with the disappearance of smaller isoforms of TCF7L2 in the liver." (PMID 23028378, 2012). "Our finding is also consistent with a previous report that TCF7L2 expression was downregulated in the livers of obese T2D mice on an HFD, suggesting that chronic insulin resistance may lead to downregulation of Tcf7l2 gene expression." (PMID 41614817, 2025). "Inactivation of TCF7L2 protein by removing the high-mobility group (HMG)-box DNA binding domain in mature adipocytes in vivo led to whole-body glucose intolerance and hepatic insulin resistance." (PMID 36514049, 2022). "Higher expression of TCF7L2 and the fatty acid desaturases FADS1, FADS2 and SCD could contribute to insulin resistance." (PMID 26087292, 2015). "TCF7L2, a trans-element of the novel XLOC_203003, a high mobility group (HMG) box-containing transcription factor and plays a key role in the WNT signaling pathway response to metabolic disturbances and glucose homeostasis, and the mediation of insulin resistance." (PMID 36290212, 2022). "Under insulin resistance, expression levels of the medium and short isoforms of TCF7L2, which reside mostly in the nucleus, are specifically reduced while no such change is observed on that of long isoforms of TCF7L2 in mouse liver." (PMID 23028378, 2012). "Similarly, while there is no direct evidence of an interaction between TCF7L2 and adiponectin, alterations in TCF7L2 that contribute to insulin resistance could influence adiponectin levels or sensitivity." (PMID 40303486, 2025). "Rather, we suspected that reduced expression of nuclear TCF7L2 by insulin resistance might be in part responsible for the enhanced hepatic glucose production, providing a potential mechanism for the hyperglycemic phenotype that is induced by DIO or genetic insulin resistance in mammals." (PMID 23028378, 2012).
colon carcinoma (42 papers, 2010 to 2025). "A colon cancer-associated single nucleotide variant in this binding site increases the binding of TCF7L2 and the expression of MYC." (PMID 36067202, 2022). "Knockdown of VBP1 also decreased TCF7L1 and TCF7L2 protein levels in Wnt-activated HCT116 colon cancer cells, which harbor an oncogenic mutation in β-catenin." (PMID 32989053, 2020). "It had been reported that in colon tumor tissue the G allele of rs11196172 was significantly related with increased expression of TCF7L2." (PMID 27769063, 2016). "Similarly, the TCF7L2 p.P370R variant was associated with a notably lower mOS, suggesting its potential involvement in driving colon cancer progression." (PMID 40658092, 2025). "We investigated cell specification in small intestinal crypts and colon tumors using conditional Tcf7l2 deletion, cell type-specific Cre recombinases, and reporter alleles in mice." (PMID 40221753, 2025). "An example of a transcription factor with increased activity in colon cancer cells is TCF7L2 (TCF4), the main transcription factor activated by Wnt signaling." (PMID 36067202, 2022). "Within the WNT pathway, individual genes evidencing association with colon cancer were WNT11 (P = 0.014) and TCF7L2 (P = 0.045)." (PMID 29986644, 2018). "Positive autoregulation has been described before for LEF1 in colon cancer, XTcf-4 (Tcf7l2) in Xenopus midbrain and zebrafish Tcf3 (Tcf7l1)." (PMID 29942461, 2018). "Twenty-nine of the 72 colon tumor-associated genes including, e.g., the Wnt-signaling-pathway genes APC, TCF7L2, and FAM123B showed significant specificity for colorectal tumors." (PMID 29296220, 2017). "Several clinical studies have reported that TCF4/TCF7L2 is an indicator of poor prognosis or malignant potential in hepatocellular carcinomas and colon cancer." (PMID 28536608, 2016). "For gained VELs in colon cancer we observe an enrichment of TCF7L2, also known as TCF4, involved in many cancer types." (PMID 25477382, 2015). "With regards to structural events in colon cancer, gene fusions of TCF7L2 with VTI1A have previously been observed in 3% of the colon cancers." (PMID 24943349, 2014). "Previous studies have used genome-wide approaches to identify TCF7L2 target genes in human colon cancer cells and, more recently, chromatin immunoprecipitation sequencing (ChIP-seq) analysis of TCF7L2 was reported in hematopoietic cells." (PMID 22951069, 2012). "However, reduction of TCF7L2 decreased transcriptional levels of Klf4 in Wnt overactivated colon tumors of mice." (PMID 40906297, 2025). "Similarly, knockdown of VBP1 in Wnt-activated HCT116 colon cancer cells also increased the interaction between TCF7L2 and pVHL." (PMID 32989053, 2020). "For the TCF7L2 dataset, there are six human cell-lines, including colon cancer cells (HCT116), embryonic kidney cells (HEK293), cervical carcinoma cells (HeLa-S3), liver cancer cells (HepG2), mammary gland adenocarcinoma cells (MCF-7) and pancreatic cancer cells (PANC-1)." (PMID 29363433, 2018). "However, in the adult colon, Tcf7l2 deletion resulted in enlarged crypts and, furthermore, Tcf7l2 haploinsufficiency promoted formation of colonic tumors in ApcMin, indicating the tumor-suppressive role of Tcf7l2." (PMID 27447672, 2016). "Interestingly, TCF7L2 gene was found to be very significantly associated with TCGA‐COAD patients in OS analysis as well as Phenolyzer analysis, emphasizing its crucial role in the progression of colon cancer." (PMID 40658092, 2025). "Notably, TMEM220-AS1, TMEM238L, SOX6, SMAD7, TCF7L2, and PYGL were significantly downregulated in colon cancer, whereas LINC02257, PCAT1, CASC8, and POU5F1B were significantly upregulated in colon cancer." (PMID 41144378, 2025). "Finally, ChIP-Seq experiments have identified β-catenin and transcription factor 7 like 2 (TCF7L2, also known as TCF4) binding regions in the Mmp20 promoter, at least in human colon cancer cells." (PMID 34778267, 2021).
colon carcinoma (continued). "In colon cancer cells, ICAT was found to compete with TCF7L2 for binding to β-catenin." (PMID 28273108, 2017). "In colon cancer cells, TCF4/TCF7L2 is located in the nucleus with beta-catenin." (PMID 28536608, 2016). "The protein derived from the TCF7L2 (transcription factor 7-like 2) gene, also known as the TCF4, is an important transcription factor in the Wnt signaling pathway, which was initially characterized in colon cancer and in the embryonic development of Drosophila, Xenopus, and other organisms." (PMID 28420445, 2017).
schizophrenia (25 papers, 2011 to 2025). A major psychotic disorder characterized by abnormalities in the perception or expression of reality. "TCF7L2 is one of the most common genes strongly associated with glucose homeostasis which also participates in the pathogenesis of schizophrenia." (PMID 35874808, 2022). "Animal studies using mice reported that the TCF7L2 gene, known as a risk factor for schizophrenia and autism, affected the connectivity and cell clustering of the thalamo-habenular region." (PMID 34539461, 2021). "SNPs in TCF7L2 have been associated with psychiatric disorders, such as schizophrenia and bipolar disorder." (PMID 31676834, 2019). "Among the TCF7L2 polymorphisms-associated metabolic disturbance, the T-allele of rs7903146 in TCF7L2 is the most consistent loci which is linked to schizophrenia and schizoaffective disorders." (PMID 29713286, 2018). "Single nucleotide polymorphisms (SNPs) in TCF7L2 (Transcription Factor 7-Like 2) reportedly affect susceptibility to schizophrenia (SCZ)." (PMID 28404897, 2017). "Consistent with a neurological function, the TCF7L2 T2D-associated interval has been implicated in schizophrenia risk." (PMID 22590553, 2012). "Recently, several converging studies reported association of different and independent genetic variants within or flanking TCF7L2 with schizophrenia." (PMID 22247771, 2012). "Polymorphism within TCF7L2 was also associated with increased risk for T2D among schizophrenia patients, in whom the disease is relatively prevalent." (PMID 22247771, 2012). "Ben-David and colleagues showed association of the rs17746501 SNP (61 kb upstream to TCF7L2) with schizophrenia in a large meta-analysis." (PMID 22247771, 2012). "A recent association study implicated variation within the Transcription factor 7-like 2 (TCF7L2) gene locus with schizophrenia risk." (PMID 22046400, 2011). "Also, ECT increases the expression of the TCF7 gene, which suppresses the function of the gene TCF7L2, which is associated with schizophrenia." (PMID 40364201, 2025). "TCF7L2 is linked to the Wnt‐signaling pathway and is associated with schizophrenia." (PMID 37807632, 2023). "Involvement of TCF7L2 as the putative effector of the altered signalling in neurons is particularly intriguing, since TCF7L2 locus has been genetically associated with mental disorders, such as schizophrenia and bipolar disorder in humans." (PMID 34503558, 2021). "In humans, polymorphisms in TCF7L2 were associated with schizophrenia and bipolar disorder." (PMID 31676834, 2019). "Recently, growing evidence suggests that Wnt signaling pathway has a critical role in the pathogenesis of schizophrenia and molecular cascades of antipsychotics action, of which Wnt signaling pathway key effector TCF7L2 is strongly associated with glucose homeostasis." (PMID 29713286, 2018). "Interestingly, a T2D risk variant in TCF7L2 has also been found to increase the risk for schizophrenia and this allele is associated with increased expression in pancreatic beta cells." (PMID 29249829, 2017). "For example, variants of the TCF7L2 gene have been associated with schizophrenia, and anxiety-like phenotypes were observed in Tcf7l2 haplo-insufficient mice, suggesting the involvement of TCF7L2 in some psychiatric disorders." (PMID 23152144, 2013). "Intriguingly, tcf7l2 has also been linked to schizophrenia and in the light of our results it is tempting to speculate about a connection between Tcf7l2 function, vHb development and schizophrenia." (PMID 24067090, 2013). "Hansen and collaborators identified significant association of a different TCF7L2 intronic variant (rs7903146) with schizophrenia in a Danish sample, and this association was replicated in a large multinational European sample of approximately 4,000 schizophrenia patients and 17,500 controls." (PMID 22247771, 2012).